HYAL2 (hyaluronidase 2)
Diseases named in the same sentence as HYAL2 in open-access papers (continued):
Sharing a sentence is not in itself a finding about the gene and the disease.
liver fibrosis (1 paper, 2022). "Together, these findings suggest that HYAL2 contributes to the abundance of LMW-HA in liver fibrosis." (PMID 35662287, 2022). "Next, we performed double immunofluorescence staining for HYAL2 and cell-specific markers in the livers of mice with CCl4-induced liver fibrosis." (PMID 35662287, 2022). "Our results suggest that elevated HYAL2 expression may contribute to liver fibrosis." (PMID 35662287, 2022). "We assessed the expression of HYAL1 and HYAL2 in liver samples from our cohort of patients with chronic HBV infection and clinically diagnosed liver fibrosis." (PMID 35662287, 2022). "HYAL2 but not HYAL1 was upregulated in patients with advanced-stage liver fibrosis." (PMID 35662287, 2022).
lung disease (1 paper, 2020). "Our study now expands the role of HYAL2 in lung disease to hypoxia-induced PH." (PMID 31937874, 2020).
Macrothrombocytopenia (1 paper, 2025). "By comparison, loss of HYAL-2 results in significant macrothrombocytopenia and dramatic accumulation of HA in the BM and MKs which impacts pro-platelet formation and increased platelet activation in response to the GPCR-agonist ADP." (PMID 41586377, 2025). "Loss of Hyal-2 resulted in to pronounced macrothrombocytopenia, significantly increased HA within the marrow, aberrant MK maturation, and reduced pro-platelet formation, which are rescued by reconstitution of hyaluronidase activity in MKs." (PMID 41586377, 2025).
mucopolysaccharidosis (1 paper, 2017). A group of autosomal recessive or X-linked inherited lysosomal storage disorders affecting the metabolism of mucopolysaccharides, resulting in the accumulation of mucopolysaccharides in the body. "This suggests that Hyal2 knockdown exhibits mucopolysaccharidosis-like OA change in articular cartilage similar to Hyal1 knockdown." (PMID 28765635, 2017).
mucopolysaccharidosis type IX (1 paper, 2020). An autosomal recessive lysosomal storage disease caused by mutation(s) in the HYAL1 gene, encoding hyaluronidase-1. "Major clinical developmental phenotypes result from mutations in hyaluronidases such as mucopolysaccharidosis type IX from Hyal1, bone defects, and cardiopulmonary dysfunction from loss of Hyal2." (PMID 31914398, 2020).
prostate neoplasm (1 paper, 2025). A neoplasm (disease) that involves the prostate gland. "Although the provided references do not directly address the association of prostate neoplasm with the ABCC5, HYAL2, and SLC9A1 proteins, it appears that the HMMR-rs299295 and STAB2-rs2271637 variants may play a role in the growth, proliferation, and metastasis of prostate neoplasm." (PMID 40567905, 2025).
pulmonary hypertension (1 paper, 2021). Increased pressure within the pulmonary circulation due to lung or heart disorder. "Another study validated this finding when vessel-derived HYAL2 promoted remodeling of the pulmonary vasculature and induced pulmonary hypertension (PH) in the absence of superoxide dismutase (SOD3), an enzyme thought to protect tissues from oxidative stress." (PMID 33809827, 2021).
renal fibrosis (1 paper, 2020). A final common manifestation of a wide variety of chronic kidney diseases characterized by glomerulosclerosis and tubulointerstitial fibrosis. "Kidneys harvested from rats that had undergone ischemia reperfusion injury–induced renal fibrosis also demonstrated positive HYAL2 staining in arterial blood vessels, and this similarly colocalized with α-Sma expression from vascular smooth muscle cells." (PMID 32201263, 2020). "To investigate the in vivo relevance of HYAL2 in progressive fibrosis, we characterized HYAL2 expression, localization, and preponderance in relation to the expression of the myofibroblast marker α-Sma in an experimental model of renal fibrosis." (PMID 32201263, 2020).
Sepsis (1 paper, 2021). Sepsis is defined as life-threatening organ dysfunction caused by a dysregulated host response to infection. "Bearing in mind the increased expression of HYAL-2, protecting the endothelial glycocalyx from HA shedding, an increasingly recognized goal in the management of sepsis and diabetes mellitus, may warrant attention in patients with COPD as well." (PMID 34354097, 2021).
serous ovarian cancer (1 paper, 2019). "We examined expression of HA synthases (HAS1, HAS2, and HAS3) and hyaluronidases (HYAL1, HYAL2) in primary serous ovarian cancer cells isolated from patient ascites and CBP-resistant OV-90 cells." (PMID 31443261, 2019). "We additionally showed that expression of HAS2 and HAS3 but not HAS1 or hyaluronidases HYAL1 and HYAL2 were significantly increased in chemoresistant compared to chemosensitive primary serous ovarian cancer cells." (PMID 31443261, 2019).
skin basal cell carcinoma (1 paper, 2020). The most frequently seen skin cancer. "The growth of skin basal cell carcinoma (BCC) tumor was blocked in mice receiving Zfra peptide or Hyal-2 antiserum (>75% inhibition)." (PMID 32764489, 2020).
tumor (49 papers, 2004 to 2025). "For instance, higher HYAL2 expression is associated with poor prognosis of triple‐negative breast cancer patients and silencing of HYAL2 expression reduces tumorigenicity in a tumor xenograft model." (PMID 37953485, 2024). "Tumor-associated endothelial cells appear to increase the expression of hyaluronidase 2 (HYAL2), one of the enzymes responsible for the degradation of hyaluronan, the main component of the endothelial glycocalyx." (PMID 38384845, 2024). "Most notably, we identify elevated levels of Hyal1 and Hyal2 in tumor-association macrophages (TAMs), suggesting a role for TAM-mediated turnover of HA in the TME." (PMID 36723776, 2023). "Instead, in the deep melanomas the tumor cells show markedly reduced amount of hyaluronan, which is associated with the increased expression of HYAL2." (PMID 23560496, 2013). "Thus, within the tumor, the myeloid cells expressing Hyal2 sustain LMW HA accumulation and tumor-associated inflammation." (PMID 37107200, 2023). "In addition, hyaluronan-enriched stroma supports the transition of tumor-recruited Hyal2+MDSCs to the PD-L1+ tumor-associated macrophages leading to the formation of an immunosuppressive and tolerogenic tumor microenvironment." (PMID 36238286, 2022). "Increased intensities of HAS2 and HYAL2 were associated with increased tumor cell proliferation." (PMID 29914429, 2018). "Localization of the gene encoding the receptor for JSRV cell entry, Hyal2, to a tumor suppressor locus in human chromosome 3 (3p21.3) led to speculation that inactivation of Hyal2 by Env might play a role in oncogenesis." (PMID 17177996, 2006). "High HAS1 expression in conjunction with low HYAL1 and HYAL2 expression was observed in the tumor stage, which resulted in the accumulation of HA around tumor cells." (PMID 39858106, 2025). "HYAL2 is not only a lysosomal protein whose enzymatic activity can be induced under acidic environments, but it is also a potential tumor suppressor." (PMID 40507943, 2025). "Some studies have shown that deregulated hyaluronan metabolism in the tumor microenvironment drives cancer inflammation, but HYAL2 has catabolic functions that can reduce excessive inflammation and contribute to the resolution of the immune response." (PMID 40563874, 2025). "HA production was also evaluated by immunohistochemistry analysis of HAS1, HAS2, HAS3, HYAL1, and HYAL2 expression on tumor cells." (PMID 39858106, 2025). "Tumor-recruited Hyal2+ myeloid cells are activated in the TME to break down HA through the translocation of Hyal2 to the cell membrane, which is dependent on the CD44 signaling pathway." (PMID 38946426, 2024). "Strikingly, F4/80 + macrophages derived from both tumor models expressed elevated levels of Hyal1 and Hyal2, suggesting that TAMs play a pivotal role in HA degradation." (PMID 36723776, 2023). "In tumoral areas, the biopolymer coating can be efficiently removed by the hydrolysis catalyzed in the first extent by hyaluronidase-2 (Hyal-2), present on cancer cells membranes, and then by hyaluronidase-1 (Hyal-1) after mediated endocytosis." (PMID 36839771, 2023). "Most notably, we identify elevated levels of the hyaluronidases Hyal1 and Hyal2 in tumor-association macrophages (TAMs), suggesting a role for TAM-mediated turnover of HA in the tumor microenvironment (TME)." (PMID 36723776, 2023). "Strong HA degradation in tumor tissues can be partially explained by increased mobilization of Hyal2+ myeloid cells in cancer patients following elevated number of Hyal2+ myeloid cells being detected in the peripheral blood." (PMID 35528727, 2022). "HYAL-1 and HYAL-2 functions are crucial in carcinogenesis; however, there is a lot of inconsistent information about their specific role in tumor growth." (PMID 36613567, 2022). "Upon recruitment to the tumor, Hyal2+ expressing myeloid cells capable of degrading extracellular HA into small fragments, promoting the accumulation of HA fragments with low molecular weight (LMW) (20 kDa)." (PMID 35528727, 2022).
tumor (continued). "Acidification also activates tumor-cell proteinases, such as matrix metalloproteinases-9, cathepsin B and hyaluronidase-2, which degrade the surrounding matrix and promote tumor cell migration." (PMID 33153193, 2020). "HYAL2, one of the enzymes that degrade hyaluronan (HA), is a tumor suppressor gene involved in cancer progression, angiogenesis, metastasis, chemokinesis, cell adhesion, and cell mobility." (PMID 33005177, 2020). "Tumor lesions showed that Hyal-2 was significantly upregulated in the WWOX knockdown BCC cells (~100% increase)." (PMID 31123603, 2019). "We also show that HAS1, HAS2 and HYAL2 are associated with WHO grade, suggesting that they have a role in tumor progression." (PMID 29914429, 2018). "In a non-canonical pathway, transforming growth factor beta (TGF-β) binds membrane Hyal-2 and then recruits tumor suppressors WWOX and Smad4, and the resulting Hyal-2/WWOX/Smad4 induces SMAD-dependent transcriptional activation in the nucleus." (PMID 27845895, 2017). "HYAL2 is known to be increased in proliferative processes and was described as a tumor suppressor gene involved in cell adhesion, cell mobility, chemokinesis, cancer progression, angiogenesis and metastasis." (PMID 28978057, 2017). "Hyal-2 is a lysosomal protein and a candidate tumor suppressor, and is also anchored on cell surface via glycosylphosphatidylinositol (GPI)." (PMID 27845895, 2017). "The immunopositivity of hyaluronidase 2 was significantly increased in the premalignant and malignant lesions indicating its specific role in the degradation of hyaluronan during tumor progression." (PMID 23560496, 2013). "The candidate region on 3p21.3 harbors various tumor suppressor genes (HYAL2, FUS1, RASSF1, BLU, NPR2L, CYB561D2, PL6 and CACNA2D2)." (PMID 20678252, 2010). "HYAL1 and HYAL2 have been shown to inhibit tumor growth in vivo, and it has been suggested that these two genes have major roles in the microenvironment of tumor cells." (PMID 20875124, 2010). "Despite their apparently divergent changes in different tumor types, HYAL2 and HYAL1 mRNA levels still correlated positively with each other in the whole patient material (r = 0.5; P = 0.0013)." (PMID 19435493, 2009). "In our SCID mice experiments HYAL1 and HYAL2 genes were inactivated (or tumours didn't grow) even when the genes were repressed (water with tetracycline)." (PMID 18725949, 2008). "As our data suggested that both HYAL1 and HYAL2 induce growth inhibition of tumours in SCID mice we tested expression of these genes in lung and renal tumours using qPCR." (PMID 18725949, 2008). "The effect of expression HYAL1 and HYAL2 was studied by colony formation inhibition, growth curve and cell proliferation tests in vitro and tumour growth assay in vivo." (PMID 18725949, 2008). "HYAL2 expression was significantly lower in tumor lesions compared with HC samples." (PMID 39858106, 2025). "HYAL1 and HYAL2 expression was significantly reduced in the tumor stage." (PMID 39858106, 2025). "HYAL1 and HYAL2 have been shown to play significant roles in the tumor microenvironment." (PMID 40507943, 2025). "In cancer, Hyal2 has tumour-suppressive functions depending on the context and tumour type." (PMID 41465475, 2025). "In addition to peripheral blood, the Hyal2-expressing myeloid cells can also be found in tumor tissue." (PMID 35528727, 2022). "Whereas upregulation of HYAL-2 inhibited tumor development in experimental lung metastases in mice." (PMID 36613567, 2022). "Studies in animals indicate that HYAL2 or HYAL1 inhibits tumor growth and may control intercellular interactions." (PMID 34540372, 2021). "Under similar experimental conditions, antiserum against WWOX at pY33 or pY287, along with Hyal-2 antiserum, reduced the BCC tumor growth in T/B-deficient NOD-SCID mice (30 to 50% reduction), suggesting that Zfra inhibits WWOX phosphorylation at Tyr33, which is needed for suppressing cancer growth." (PMID 32764489, 2020).
tumor (continued). "We show that HAS1, HAS2 and HYAL2 associate with tumor grade (WHO II-IV), and HAS2 is a negative prognostic factor in diffusely infiltrating astrocytomas." (PMID 29914429, 2018). "Furthermore, the methylation level of HYAL2 in tumor tissue has been shown to predict overall and progression-free survival in colorectal cancer." (PMID 28978057, 2017). "Hyaluronidases PH-20, Hyal-1 and Hyal-2 induce the expression of tumor suppressor WWOX." (PMID 27845895, 2017). "For example, the overexpression of Hyal 1 inhibited tumorigenesis in rat colon cancer cells, while adenovirus-mediated expression of Hyal 2 could suppress tumor growth in mice." (PMID 29062810, 2017). "Indeed, activation of hyaluronan degrading enzyme, HYAL2, led to a reduction in the high molecular mass hyaluronan, which resulted in tumor promotion in this model." (PMID 27184066, 2016). "Transgenes were detected only in one tumour (HYAL2) and in eleven tumours it was deleted." (PMID 18725949, 2008). "HYAL2 was inoculated into 12 mice and only four tumours were obtained." (PMID 18725949, 2008). "As major hyaluronidases in human cells, HYAL1 and HYAL2 may control intercellular interactions and microenvironment of tumour cells providing excellent targets for cancer treatment." (PMID 18725949, 2008). "Moreover, HYAL2 is related to tumor biology and angiogenesis." (PMID 40646377, 2025). "Regulated uptake of hyaluronan via a CD44 receptor-mediated endocytosis pathway and subsequent degradation by HYAL2 may be important for tumor growth and progression either through the stimulation of angiogenesis or through degradation of HA around blood vessels promoting tumor metastasis." (PMID 24083250, 2013). "In breast cancer, augmented enzymatic activity of HYAL1 and HYAL2 correlates with aberrant signaling through HA receptors (CD44, RHAMM), thereby promoting tumor progression, metastasis, and recurrence." (PMID 40646377, 2025). "We first analyzed HA synthases HAS1, HAS2, and HAS3, hyaluronidases HYAL1 and HYAL2, ABCC5 transporter, and CD44 expression in tumor tissue (TT) in TCGA database." (PMID 39039104, 2024). "This is consistent with the fact that HYAL2 overexpression and its hyaluronidase activity can generate LMW-HA fragments, which encourage tumor cell proliferation and invasion." (PMID 37334363, 2023). "Since HA undergoes dynamic regulation by HYALs, we evaluated the expression of HYAL1, HYAL2, and HYAL3 by RT-qPCR in three normal pancreatic tissue samples and seven PDAC tumor specimens." (PMID 37296612, 2023). "In contrast, the expression of HAS2 (fold change = 1.42), HYAL2 (fold change = 1.84) and HYAL3 (fold change = 1.94) was significantly increased in the tumour tissue." (PMID 35767191, 2022). "In the tumour tissue, 3 of 12 and 11 samples, respectively, showed low to medium HYAL1 and HYAL2 expression, being undetectable in the remaining samples." (PMID 35767191, 2022). "During a prolonged treatment of nude mice with Zfra for two months, downregulation of Hyal-2, and reduction in TMR-Zfra-positive Z cells occurred in the spleen, suggesting that Z cells relocate to a tumor-growing organ." (PMID 32764489, 2020). "We also provide the regulatory role of tumor suppressor WWOX in the upstream of TGF-β, Hyal-2, and Wnt signaling that cross talks with the Hippo pathway." (PMID 30805310, 2019). "In a non-canonical signaling, TGF-β binds membrane hyaluronidase Hyal-2 for recruiting tumor suppressors WWOX and Smad4, and the resulting Hyal-2/WWOX/Smad4 complex is accumulated in the nucleus to enhance SMAD-promoter dependent transcriptional activity." (PMID 27845895, 2017). "In tumour T10 where the HYAL2 gene was present by PCR, there was no detectable expression by Northern (data not shown)." (PMID 18725949, 2008). "Despite these differences main results are similar to our work: HYAL1 and HYAL2 do not have strong growth inhibiting activity in vitro and HYAL2 displayed some tumour suppressor activity in vivo." (PMID 18725949, 2008).
tumor (continued). "In contrast to the tumour suppressor function of HYAL1 and HYAL2 in these studies, no frequent inactivating mutations were identified so far in these genes." (PMID 18725949, 2008). "The results showed that HYAL1 and HYAL2 did not significantly inhibit tumour cells growth neither in vitro nor in vivo." (PMID 18725949, 2008). "When comparing TT and NAT, we noticed a high variability of HAS2, HAS3 and HYAL2 among the patients for both tumor types while HAS1 and HYAL3 could not be detected." (PMID 32610620, 2020). "At the end point of tumor growth experiments, Zfra significantly suppressed the expression of Hyal-2 and phosphorylation of WWOX at Y33 and Y61 (>90%), but no significant changes were observed for WWOX phosphorylation at S14 and Y287 in the spleen of the sacrificed mice (<5%)." (PMID 32764489, 2020). "In preclinical studies, for instance, overexpression of HYAL2 has been observed to stimulate tumor growth in a mouse model of astrocytoma, and Tan and co-workers have reported that HYAL1 overexpression promotes tumor growth and angiogenesis in a breast cancer xenograft model." (PMID 24213471, 2012).